GSTM1 (glutathione S-transferase mu 1)
Diseases named in the same sentence as GSTM1 in open-access papers (continued):
Sharing a sentence is not in itself a finding about the gene and the disease.
prostate carcinoma (continued). "Numerous studies have evaluated the association between GSTM1 null/present polymorphism and risk of prostate cancer (PCa)." (PMID 23071687, 2012). "Double null genotype GSTM1/GSTT is associated with a higher risk of prostate cancer in Asians." (PMID 36824501, 2023). "The aim of this study was to investigate whether mutations in GSTM1, T1, and the androgen-receptor gene and the androgen-receptor filamin protein A complex are associated with prostate cancer patients." (PMID 36824501, 2023). "Significantly increased prostate cancer risk was found among subjects carrying GSTM1 null genotype (odds ratio (OR) = 1.403; 95% confidence interval (CI) = 1.088 – 1.808) but not among subjects carrying GSTT1 deletion genotype (OR = 0.959; 95%CI = 0.709 – 1.297)." (PMID 26416453, 2015). "A higher copy number of GSTM1 was marginally associated with prostate cancer risk." (PMID 25198353, 2014). "So we may hypothesize that in a larger population GSTM1 null polymorphism may act as slight hazard for prostate cancer BCR." (PMID 24086370, 2013). "Additionally, the occurrence of the GSTM1-null genotype can elevate the risk of prostate cancer." (PMID 37819495, 2023). "The results showed that specific mutations and SNPs in GSTP1, GSTM1, and GSTT1 have been linked to an increased risk of prostate cancer." (PMID 37175108, 2023). "Recent studies have assessed the combined effects of GSTM1 and GSTT1 genotypes, but few studies have shown a significant association between the defects in these genes and prostate cancer risk." (PMID 36824501, 2023). "Gene polymorphisms of GSTM1, GSTT1, GSTO1 rs4925, GSTO2 rs156697, GSTP1 rs1695, and GSTP1 rs1138272 and risk of overall mortality in prostate cancer patients by Cox proportional hazards regression models." (PMID 33937322, 2021). "The deletion of GSTM1 was found in ca. 47% of patients with prostate cancer and in ca. 55% of controls." (PMID 32212077, 2020). "The GSTM1 gene deletion was found in ca. 47% of patients with prostate cancer and in ca. 55% of the controls." (PMID 32212077, 2020). "The aim of the study was frequency analysis of GSTM1, GSTT1, and GSTP1 polymorphisms of glutathione S-transferase in the group of patients with prostate cancer and in a control group of healthy individuals." (PMID 32212077, 2020). "Deletion of GSTM1 gene at stage IV prostate cancer patients was significantly higher compared with other stages of cancer while no significance was shown by GSTT1 gene deletion." (PMID 26600754, 2015). "The current study was aimed to find out the association of GSTM1 and GSTT1 gene polymorphisms with prostate cancer in Pakistani men." (PMID 26600754, 2015). "GSTM1 and GSTT1 gene polymorphisms have been studied in many populations to evaluate their association with prostate cancer risk with contrasting results." (PMID 26600754, 2015). "Deletions of the glutathione S-transferase genes M1 and T1 (GSTM1 and GSTT1) have been studied as potential risk factors for prostate cancer." (PMID 25198353, 2014). "Extensive research has been carried out, mostly in Caucasian and Asian populations, studying the relationship between GSTM1 and GSTT1 polymorphisms and prostate cancer risk." (PMID 25198353, 2014). "By contrast, the interaction between GSTM1 or the sum of GSTM1/GSTT1 copy numbers and alcohol consumption resulted in a tendency towards an increase in the risk of prostate cancer restricted to former or current drinkers." (PMID 25198353, 2014). "Using subjects with homozygous deletion of both GSTM1 and GSTT1 genes as the reference group, adjusted models indicated that subjects carrying both genes were at significantly higher risk of prostate cancer (OR: 1.88, 95% CI: 1.11–3.21)." (PMID 25198353, 2014). "Association between copy number of the sum of GSTM1/GSTT1 genes and risk of prostate cancer according to smoking, alcohol consumption, body mass index and family history of prostate cancer." (PMID 25198353, 2014).
prostate carcinoma (continued). "The most recent meta-analysis, mostly grouping studies conducted with Caucasian and Asian men, suggest that homozygous deletion of the GSTM1 and GSTT1 genes is associated with increased risk of prostate cancer." (PMID 25198353, 2014). "Men with 3, 4 and 5 or more copies of both GSTM1 and GSTT1 genes were at higher risk of prostate cancer (OR: 2.18, 95% CI: 1.21–3.91, OR: 3.24, 95% CI: 1.63–6.46, and OR: 5.77, 95% CI: 1.40–23.84, respectively; Ptrend<0.001)." (PMID 25198353, 2014). "Not only did our study not confirm these findings, but it even leads to the opposite conclusion for this population of African descent: there was a positive association between GSTM1 or GSTT1 copy number and the risk of prostate cancer." (PMID 25198353, 2014). "Here, we report the continuation of this case-control study by determining the exact gene copy numbers of GSTM1 and GSTT1 genes and investigating the associations between the CNV of each gene and the risk of prostate cancer." (PMID 25198353, 2014). "Studies have investigated whether certain genetic alterations in Glutathione S-transferases (GSTs)—GSTP1, GSTM1, and GSTT1—that play a role in carcinogen metabolism and defense against reactive oxygen species are linked to prostate cancer risk." (PMID 37175108, 2023). "Men with a GSTM1 deletion genotype, a GSTM1 and GSTT1 double deletion genotype, or a GSTT1 deletion gene and the GSTP1-A131 G polymorphism have an increased risk of developing prostate cancer." (PMID 36824501, 2023). "The latest meta-analysis by Cai and co-workers 2014 also showed significant relationships between prostate cancer and GSTM1 polymorphism in Caucasians and the lack of such correlations for GSTT1 allele." (PMID 32212077, 2020). "Therefore, we performed a comprehensive analysis of GSTM1 and GSTT1 deletion polymorphisms, as well as of GSTP1 rs1138272 and GSTP1*IIe105Val rs1695 polymorphisms in a cohort of 237 prostate cancer cases and 236 age-matched controls." (PMID 32183092, 2020). "The goal of this study was to determine whether the GSTM1, GSTT1, and GSTP1 polymorphisms can modify the risk of developing prostate cancer." (PMID 32212077, 2020). "In relation to prostate cancer, there are no consistent associations between GSTM1, GSTT1 or GSTP1 genotypes and related studies produced as recent as 2012 give the same information." (PMID 27043589, 2016). "The current study through meta-analysis indicated that significantly elevated prostate cancer risk was associated with GSTM1 rather than GSTT1 null genotype." (PMID 26416453, 2015). "Despite some limitations, this meta-analysis suggested that the GSTM1 null genotype was associated with enhanced risk of prostate cancer carcinogenesis, but non-significant association was observed for GSTT1 deletion with prostate cancer risk." (PMID 26416453, 2015). "Men with at least 3 GSTM1 genes were at a higher, but not significantly higher, risk of prostate cancer (OR: 2.55, 95% CI: 0.78–8.39); the trend for GSTM1 gene dose association was inconclusive (Ptrend 0.17)." (PMID 25198353, 2014). "Furthermore, a higher combined GSTM1 and GSTT1 copy number appears to be significantly associated with an increased risk of prostate cancer." (PMID 25198353, 2014). "Association between copy number of the GSTM1 and GSTT1 genes and risk of prostate cancer." (PMID 25198353, 2014). "We recently described a population-based case-control study in Guadeloupe among a Caribbean population of African descent showing that homozygous deletions of GSTM1 and those of GSTT1 are each, independently, significantly associated with a reduced risk of prostate cancer." (PMID 25198353, 2014). "We investigated whether copy number variation (CNV) of the GSTM1 and/or GSTT1 genes contribute to the risk of prostate cancer in the Caribbean population of African descent of Guadeloupe." (PMID 25198353, 2014).
prostate carcinoma (continued). "For GSTM1 null polymorphism, none of the four included studies suggested a significant association with biochemical recurrence of prostate cancer." (PMID 24086370, 2013). "In contrast, a number of meta-analyses indicate no marked associations of GSTM1 gene polymorphism with hepatocellular carcinoma, gastric cancer, esophageal cancer and prostate cancer." (PMID 22900055, 2012). "Distribution of GSTP1, GSTT1 and GSTM1 genotypes in controls and patients with prostate cancer." (PMID 19265530, 2009). "However, various meta-analyses have not detected any marked association between null GSTM1 mutation, and hepatocellular carcinoma esophageal cancer or prostate cancer." (PMID 32882964, 2020). "However, such significant connection between GSTM1 null genotype and increased prostate cancer risk were not present in Japan subjects (OR = 0.980; 95%CI = 0.726 – 1.321)." (PMID 26416453, 2015). "Importantly, statistically significant association of increased prostate cancer risk with GSTM1 deletion was still not substantially altered (OR = 1.567; 95%CI = 1.320 – 1.860)." (PMID 26416453, 2015). "Then we found similar non-significant relationship between GSTT1 deletion and prostate cancer risk among in china, Korea, and Japan, while significant association of null genotype of GSTM1 with increased prostate cancer risk was detected in China and Korea but not in Japan." (PMID 26416453, 2015). "Our results indicate: first, that higher copy number of GSTM1 tends to be associated, although not significantly, with an increased risk of prostate cancer; and second, that higher copy number of GSTT1 is significantly associated with an increased risk of the disease." (PMID 25198353, 2014). "Finally, men with 3, 4, and 5 or more copies of GSTM1 and GSTT1 genes were at significantly increased risk of prostate cancer (OR: 2.18, 95% CI: 1.21–3.91, OR: 3.24, 95% CI, 1.63–6.46, and OR: 5.77, 96% CI: 1.40–23.8, respectively) and there was a significant gene dose relationship (Ptrend<0.001)." (PMID 25198353, 2014). "However, a number of meta-analyses suggest no marked associations of GSTM1 null mutations with hepatocellular carcinoma, brain tumors, gastric cancer, esophageal cancer and prostate cancer." (PMID 19338664, 2009). "There was a statistically significant difference in the prostate cancer group with more than two copies of the GSTT1 and GSTM1 genes compared to the normal control group." (PMID 36824501, 2023). "In this study, TC-type and CC-type prostate cancer patients had higher expression level of androgen-receptor filamin A complex and higher copy numbers of GSTT1 and GSTM1." (PMID 36824501, 2023). "In the prostate cancer group, the number of subjects with GSTT1 gene copy numbers of 0, 1, 2, and > 2 was 33, 25, 16, and 11, respectively, and the number of subjects with GSTM1 gene copy numbers of 0, 1, 2, and > 2 was 46, 20, 10, and 9, respectively." (PMID 36824501, 2023). "The aim of this study was to analyze the frequency of polymorphic glutathione S-transferase (GSTM1, GSTT1, GSTP1) in patients with prostate cancer compared with the control group of healthy men from Poland." (PMID 32212077, 2020). "GSTM1, GSTM3 and ABCC6 were metabolism related genes whose abnormal regulation may contribute to prostate cancer progression." (PMID 29190897, 2017). "GSTM1, GSTT1 and deletion of both GSTM1 and GSTT1 genes do not contribute towards increased risk of prostate cancer in Pakistani population." (PMID 26600754, 2015). "Only one previous study assessed the relationship between the GSTM1 and GSTT1 copy numbers and prostate cancer: it was a prospective study (The Copenhagen City Heart Study) of a Caucasian population of Danish descent and included 128 cases of prostate cancer." (PMID 25198353, 2014). "Some studies, which combined data from other genotypes, have shown that the concurrent lack of GSTM1/GSTT1 and GSTP1 genes posed a significantly increased risk of prostate cancer." (PMID 19265530, 2009).
prostate carcinoma (continued). "In turn, in the case of studies conducted on the Algerian population, it was observed that the GSTM1-null genotype may increase the susceptibility to this cancer, but the GSTT1 null genotype has not contributed to the development of prostate cancer." (PMID 37819495, 2023). "In summary, this meta-analysis suggested that the null genotype of GSTM1 rather than GSTT1 may be involved in the etiology of prostate cancer in Asian population." (PMID 26416453, 2015). "We did not observe significantly different crude rates of the GSTM1 and GSTT1 null genotypes in the men diagnosed with prostate cancer and those in the control group." (PMID 19265530, 2009). "In the present study, we did not observe significantly different crude rates of the GSTM1 and GSTT1 null genotypes in the men diagnosed with prostate cancer and those in the control group." (PMID 19265530, 2009).
colorectal cancer (34 papers, 2007 to 2025). A primary or metastatic malignant neoplasm that affects the colon or rectum. "The GSTM1 null genotype has been associated with several cancers including cancers of the colorectum, oral cavity, lung, cervix, and stomach." (PMID 34234117, 2021). "In the colorectal dataset, GSTM1 demonstrated a high negative correlation in all stages prior to stage T4a, whereas in stage T4b this was completely lost, suggesting that low levels of GSTM1 are associated with the onset and progression of colorectal cancer." (PMID 30578123, 2019). "This has been confirmed in different populations, where the GSTM1 null variant was correlated with increased colorectal cancer risk." (PMID 30578123, 2019). "This association was also seen between GSTM1 null and other cancers such as breast, lung and colorectal cancers." (PMID 31646988, 2019). "In our meta-analysis, 33 eligible studies with 8502 colorectal cancer patients and 13699 healthy controls were pooled to calculate the association between GSTM1 polymorphism and colorectal cancer." (PMID 26219826, 2015). "In summary, the meta-analysis suggested that GSTM1 null polymorphism confer the susceptibility to colorectal cancer in Asians, especially in Chinese populations." (PMID 26219826, 2015). "We searched the PubMed database with GSTM1, polymorphism and colorectal cancer, attempting to identify the eligible studies." (PMID 26219826, 2015). "Inclusive of 33 case-control studies, the present meta-analysis was performed to further explore the relationship between GSTM1 null variant and the susceptibility to colorectal cancer more comprehensively in Asians." (PMID 26219826, 2015). "The pooled meta-analysis suggested that GSTM1 null variant was correlated to the colorectal cancer risk in Asians." (PMID 26219826, 2015). "There were many association studies on relationship between GSTM1 null polymorphism and colorectal cancer in various ethnicities." (PMID 26219826, 2015). "Significant association between GSTM1 null variant and colorectal cancer in Asian populations was observed in the pooled meta-analysis under both fixed-effect model and random-effect model." (PMID 26219826, 2015). "Nevertheless, cumulative meta-analysis observed a trend of an obvious association between the GSTM1 null genotype and colorectal cancer risk in Asians." (PMID 26219826, 2015). "On the other hand, a 5-fold increased risk of colorectal cancer was reported for simultaneous carriers of both GSTM1 and GSTT1 null genotypes in a study of 144 cases and 329 healthy controls in Spain." (PMID 20534171, 2010). "Thus, the GSTM1-null genotype is associated with the risk of developing nasopharyngeal carcinoma and significantly shorter survival in patients with colorectal cancer." (PMID 39125992, 2024). "As far as the intervention’s ability to reduce colorectal cancer risk by reducing damage to cellular DNA is concerned, those with the GSTM1, NQO1, and GSTT1 variants are more likely to benefit from consuming PHYTOME meat over standard processed red meat products." (PMID 38337709, 2024). "Moreover, it has been suggested that GSTM1-null genotype is an important genetic risk factor for gastric, lung and colorectal cancer development." (PMID 38068321, 2023). "The pooled meta-analysis, the cumulative meta-analyses by publication year and the sample size, and the sensitivity analysis correspondingly supported the GSTM1 null polymorphism contribute the genetic risk to colorectal cancer in Asians, especially in Chinese." (PMID 26219826, 2015). "Furthermore, the cumulative meta-analysis accumulated by publication year or the sample size further confirmed the obvious association of the GSTM1 null variant colorectal cancer in Asians." (PMID 26219826, 2015).